GPX1 (glutathione peroxidase 1)
Diseases named in the same sentence as GPX1 in open-access papers (continued):
Sharing a sentence is not in itself a finding about the gene and the disease.
diabetes (42 papers, 2007 to 2025). "A deficiency in or the reduced activity of GPx1 have been associated with an increased risk of cardiovascular diseases, diabetes and metabolic syndrome." (PMID 38542762, 2024). "The effectiveness of GPx1 mimics to reduce the inflammatory components of diseases have been documented in diabetes-associated cerebral ischemia‒reperfusion injury and atherosclerosis." (PMID 38483584, 2024). "Studies have shown that overexpression of GPX1 can protect mice under oxidative stress, but it can still cause obesity and diabetes." (PMID 35132345, 2022). "In the context of the ApoE knockout on a Western diet, knockdown of GPx1 accelerated atherosclerosis in mice as well as in mice with streptozotocin-induced diabetes, indicating that in susceptible models GPx1 regulates atherogenesis." (PMID 34579115, 2021). "In the same way, a recent meta-analysis confirms the association of GPx1 variants with CAD in people with type 2 diabetes mellitus of Chinese and Indian populations." (PMID 27067415, 2016). "Diabetes caused a significant increase in the amount of nitrotyrosine immunostaining in the aortic sinus region of ApoE/GPx1 dKO mice (P<0.05)." (PMID 23874911, 2013). "In this study, we now confirm and expand on our initial findings by demonstrating that ME, in an analogous fashion to the parent compound Eb, reduces oxidative stress and diabetes-associated atherosclerosis in the diabetic ApoE/GPx1 dKO mouse." (PMID 23874911, 2013). "Armed with this knowledge, our group was particularly interested in the role of Gpx1 in vascular complications associated with diabetes." (PMID 22013533, 2012). "The role of oxidative stress in diabetes-associated atherosclerosis was confirmed in experiments on apoE-/- mice deficient for one of the main regulators of antioxidant enzymes, glutathione peroxidase 1 (Gpx1)." (PMID 32155866, 2020). "Upon diabetes induction with streptozotocin, animals that were also deficient for Gpx1 had accelerated atherogenesis, with increased plaque size, macrophage infiltration, and increased expression of inflammatory markers, while restoration of Gpx1 reduced atherogenesis." (PMID 32155866, 2020). "CAT rs7943316 and GPX-1 rs1050450 polymorphisms alter their antioxidant capacity and associated with different kinds of diseases such as Kashin-Beck, prostate cancer, peripheral neuropathy, diabetes mellitus recurrent miscarriage, and brain tumors." (PMID 30524988, 2018). "Furthermore, our recent study showed that Eb significantly attenuates pro-inflammatory and pro-atherosclerotic mediators as well as diabetes-associated atherosclerosis and diabetic nephropathy after 20 weeks of treatment in the diabetic ApoE/GPx1 dKO mice." (PMID 23874911, 2013). "Importantly, in our studies, ebselen was able to significantly improve diabetes-associated atherosclerosis and nephropathy in our ApoE/GPx1 dKO mice." (PMID 22013533, 2012). "Oral administration of EeSs boosted the expression of Sod1, Cat, Gpx-1, Hmox-1, and Nqo-1 mRNA levels in the diabetic mice liver, suggesting that EeSs has a strong antioxidant potential to quince free radicals and hence the ability to prevent diabetes-associated complication." (PMID 28607575, 2017). "Ebselen has been shown to reduce diabetes-related atherosclerosis in double knockout (apolipoprotein E/GPx1) mice." (PMID 38483584, 2024). "Here, we showed that retinal GPx1 promoter DNA is hypermethylated in diabetes and that SAM levels are elevated." (PMID 38539790, 2024). "GPx1 is involved in regulating insulin synthesis and secretion, insulin sensitivity, glucose and lipid homeostasis and the onset and progression of diabetes." (PMID 36438755, 2022). "In this context, the study focusing on the relationship between selenoproteins and diabetes has received considerable attention, indicating unsuspected key roles of SELENOP and GPX1 in diabetes." (PMID 34445217, 2021).
diabetes (continued). "In the multivariable analysis including GPX1 rs1050450, AH and diabetes, both GPX1 rs1050450 (p = 0.014) and patients’ clinical characteristics remained significantly associated with the IOP (p < 0.001 and p = 0.019, respectively)." (PMID 33803434, 2021). "Similar to GPX1, MSRB1 has been shown to act in the Se-mediated regulation of energy metabolism and diabetes risk." (PMID 34679693, 2021). "Intriguingly, it was confirmed that KCa3.1 expression was elevated by ROS overproduction in the endothelium under HG and/or diabetes conditions, while crocin significantly suppressed this elevation by promoting GPx1 and subsequently eliminating ROS generation." (PMID 33777959, 2021). "Recent studies indicate that excess Gpx1 and Selenop exacerbate glucose metabolism and promote type 2 diabetes mellitus." (PMID 32604760, 2020). "Specifically, the overexpression of glutathione peroxidase 1 has undesirable effects to insulin- induced signaling pathways consequently promoting type 2 diabetes mellitus." (PMID 28373910, 2017). "By contrast, results from mice engineered to be Gpx1 null or overexpression with 28‐fold activity increase in the pancreas collectively implicate Gpx1 in diabetes promotion." (PMID 27653523, 2017). "The high activity of GPx1 can interfere with insulin signaling, which is critical to the regulation of glucose levels and the prevention of diabetes." (PMID 25880386, 2015). "We have previously shown that 20 weeks of diabetes significantly enhances pro-inflammatory and pro-atherogenic mediators as well as atherosclerosis and diabetic kidney disease in ApoE/GPx1 dKO mice." (PMID 23874911, 2013). "The generation of GPx1 KO mice by our group and others have specifically demonstrated the importance of GPx1 in protecting the vasculature against oxidative stress and vascular complications of diabetes." (PMID 22013533, 2012). "In order to achieve these aims, we generated ApoE/GPx1 double KO (dKO) mice and rendered them diabetic using STZ, which proved to be a robust model for diabetes-associated atherosclerosis and nephropathy." (PMID 22013533, 2012). "Data are accumulating to link alteration or abnormality of GPx-1 expression to etiology of cardiovascular disease and diabetes." (PMID 17825092, 2007). "Thus, elevated homocysteine in diabetes hypermethylates GPx1 promoter, thus decreasing the mitochondrial GPx/GSH pool and exacerbating mitochondrial damage." (PMID 38539790, 2024). "In ApoE/mice, a lack of functional Gpx1 accelerated diabetes-associated atherosclerosis by upregulating proinflammatory and profibrotic pathways." (PMID 36902173, 2023). "Interestingly however, β-cell-specific overexpression of GPx1 reverses diabetes in db/db mice, which means that systemic and local modulations of GPx1 activity have markedly distinct effects." (PMID 37373256, 2023). "The role of glutathione peroxidase isoforms other than GPX1 in the development of diabetes remains unknown." (PMID 36902173, 2023). "Furthermore, studies in patients with T2DM suggest that GPx-1 is an essential enzyme that plays a protective role in the development of endothelial dysfunction and atherosclerosis in diabetes." (PMID 37107209, 2023). "In the diabetic apolipoprotein E-deficient mouse model, decreased levels or lack of GPx-1 accelerate diabetes-associated atherosclerosis." (PMID 37107209, 2023). "Increased Gpx1 and Selenop are significant therapeutic targets for type 2 diabetes mellitus." (PMID 32604760, 2020). "In a diabetic apolipoprotein E-deficient mouse model, decreased levels or lack of GPx-1 accelerates diabetes-associated atherosclerosis." (PMID 31210841, 2019). "Investigation of connection between GPx-1 polymorphism and development of atherosclerosis in 184 Japanese patients with the T2DM show that GPx-1 is the most important enzyme, with the protective role in the development of endothelial dysfunction and atherosclerosis in diabetes." (PMID 31210841, 2019).
diabetes (continued). "Furthermore, the overexpression of antioxidant enzymes, such as glutathione peroxidase-1 (GPx-1), in an animal model of diabetes provided protection against hyperglycemia-induced oxidative stress." (PMID 27092078, 2016). "Consequently, we investigated the effects of ME in an in vivo model of diabetes, the ApoE/GPx1 double knockout (dKO) mouse." (PMID 23874911, 2013). "In addition, overproduction of GPX1 may be beneficial in the event of diabetes or obesity." (PMID 37132140, 2024). "GPX1 immunoreactivity in islet cells corresponded to staining patterns 1 (grades 1–3) and 2 (grades 4–6), irrespective of diabetes status." (PMID 40059238, 2025). "Interestingly, crocin could significantly promote GPx1 expression and activation, suggesting that elimination of H2O2 is a crucial event in the process by which crocin reduces excessive ROS in diabetes." (PMID 33777959, 2021).
Hyperglycemia (40 papers, 2010 to 2024). An increased concentration of glucose in the blood. "Hyperglycemia causes reduction in the GPx-1 gene, which encodes the glutathione peroxidase-1 enzyme, crucial in preventing oxidative stress and endothelial dysfunction." (PMID 37341768, 2023). "Hyperglycemia upregulates miRNA-185 with reduction of the GPx-1 gene, which encodes the glutathione peroxidase-1 enzyme, which is important in preventing oxidative stress and endothelial dysfunction." (PMID 35562979, 2022). "Excessive GPX1 activity may be detrimental to T2D and obesity, as demonstrated by the positive association between the overexpression of GPx1 and the impaired glucose clearance, hyperinsulinemia, hyperglycemia, and reduced insulin signaling in a mouse model." (PMID 35740085, 2022). "Our results show that, in addition to the reduction in GPx activity, gene transcripts of GPx1 are also decreased in hyperglycemia, and additional homocysteine further reduces GPx1 gene transcripts." (PMID 38539790, 2024). "In a mouse model of hyperlipidemia and hyperglycemia (apolipoprotein E/GPx1 (ApoE(−/−)GPx1(−/−))-double knockout (dKO) mice), ebselen significantly reduces NOX2 and oxidative stress ameliorating fibrosis and inflammation in the kidney." (PMID 36829988, 2023). "Mice with the elevated expression of a major antioxidant selenoprotein (GPX1) showed hyperglycemia, hyperinsulinemia, elevated body fat accretion and plasma leptin and reduced insulin sensitivity." (PMID 36978903, 2023). "Intriguingly, pancreatic islet cells produce a relatively low amount of antioxidant enzymes including GPx1 and SOD and β cells are susceptible to oxidative stress that can be induced by hyperglycemia." (PMID 28763492, 2017). "Importantly, it has been established that overexpression of GPx-1 in beta cells of diabetic mice (db/db) preserved their mass and reversed the development of hyperglycemia." (PMID 38257166, 2024). "We studied whether an increase in GPx-1 in beta cells specifically would protect them from the adverse effects of chronic hyperglycemia." (PMID 36834496, 2023). "Hyperglycaemia enhances the O-GlcNAc modification of GPX1 and subsequently increases the association between non-receptor tyrosine kinase c-Abl and Arg in rat vascular smooth muscle cells." (PMID 35203353, 2022). "Transgenic mice overexpressing GPx1 developed hyperglycemia, and obesity, which may then trigger systemic inflammation and consequently OA." (PMID 36699932, 2022). "Furthermore, it has been shown that the activities of Glutathione peroxidase 1 (GPX1) is induced by hyperglycaemia." (PMID 35203353, 2022). "Increased circulating levels of SELENOP might contribute to future hyperglycemia by inducing the other selenoproteins such as GPX1." (PMID 30425271, 2018). "Moreover, the overexpression of GPX1 in mouse increases body weight and fat content, hyperglycemia, and hyperinsulinemia and reduces insulin sensitivity." (PMID 29675131, 2018). "However, an increase in GPx1 activity can potentially disrupt insulin function by excessively suppressing intracellular ROS required for insulin sensitization, ultimately leading to hyperglycemia." (PMID 38408934, 2024). "Our results showed that intracellular oxidative stress in hyperglycemia was overexpressed, while FoxO1, SIRT1, GPX1, and SOD2 were downregulated." (PMID 36057883, 2022). "SIL promotes the expression of SIRT1, FoxO1, CAT, GPX1 and SOD2 of hyperglycemia Intervention of MC3T3-E1 by reducing intracellular ROS levels and restoring the activity and function of MC3T3-E1, similar to those from some researches." (PMID 36057883, 2022). "In the current study we shown that under hyperglycemia condition antioxidants like NQO1, SOD1 were upregulated and Gpx1 was down regulated and upon vitamin-D treatment this conditioned were normalized." (PMID 36358486, 2022).
Hyperglycemia (continued). "In this regard, hepatocyte-specific deletion of glutathione peroxidase 1 (GPX1), an enzyme located in the mitochondrial matrix and cytosol that eliminates H2O2, protected mice from diet-induced NASH and hyperglycemia." (PMID 33276146, 2021). "By contrast, after overexpressing GPx1 in pancreatic β cells, C57BLKS/J mice were protected from the β cell damage when stimulated with streptozotocin, and db/db mice exhibited reversed hypoinsulinemia and hyperglycemia." (PMID 36438755, 2022). "Interestingly in contrast to HUVEC, the gene expression of ROS clearance enzymes, SOD1, GPX1, TXNRD1, TXNRD2, and PRDX1 were upregulated in HMVEC under hyperglycemia." (PMID 24093550, 2013). "In addition, hyperglycaemia and dyslipidaemia perturbs renal antioxidant capacity by lowering glutathione (GSH), glutathione peroxidase-1 (GPx1), superoxide dismutase-1 (SOD1), and catalase (CAT) that subsequently induce lipid peroxidation, protein damage, and chronic inflammation." (PMID 38139208, 2023).
atherosclerosis (34 papers, 2007 to 2025). A disease characterized by the build-up of fatty material and calcium deposition in the arterial wall resulting in partial or complete occlusion of the arterial lumen. "Plasmalogen enrichment via batyl alcohol supplementation attenuated atherosclerosis in ApoE- and ApoE/GPx1-deficient mice." (PMID 39247623, 2024). "GPx1 levels are decreased in diabetic rats and the deficiency of GPx1 accelerates atherosclerosis by enhancing pro-inflammatory and pro-fibrotic mechanisms in cardiovascular system." (PMID 31620092, 2019). "Mice deficient in GPx1 (GPx1−/−/ApoE−/−) developed significantly more atherosclerosis than the control apolipoprotein E-deficient mice." (PMID 24683439, 2014). "GPx-1 deficiencies also have deleterious effects in atherosclerosis." (PMID 40227195, 2025). "GPx1 is found in many cell types, and its deficiency has been linked with atherosclerosis." (PMID 33639960, 2021). "GPx-1 deficiency was found to have deleterious effects also in the context of atherosclerosis." (PMID 30140678, 2018). "Risk of vascular calcification and atherosclerosis is also affected by Leu allele of GPX1 SNPs." (PMID 26881045, 2016). "GPx-1 deficiency accelerates atherosclerosis and increases lesion cellularity in ApoE−/− mice." (PMID 23991041, 2013). "Deletion of the Gpx1 in atherosclerosis-prone apolipoprotein E-deficient (ApoE−/−) mice caused accelerated atherosclerotic plaque formation and enhanced vascular oxidative stress, whereas Gpx1 deficiency in wildtype mice resulted in more pronounced aging-associated complications." (PMID 32408480, 2020). "The fact that the impact of GPx-1 deficiency on macrophage proliferation could be abolished by the GPx mimic ebselen (5 A) opens novel avenues of therapeutic strategies against atherosclerosis." (PMID 23991041, 2013). "GPX-1 deficiency increased oxLDL-induced foam cell formation and lesion cellularity and accelerated atherosclerosis in GPX1−/−ApoE−/− mice through the p44/42 MAPK (p44/42 mitogen-activated protein kinase) pathway." (PMID 37509649, 2023). "The cardioprotective role of GPx-1 is manifested by preventing oxidative stress-induced atherosclerosis." (PMID 35138466, 2022). "The importance of Gpx1 in protecting against atherosclerosis has been established in this model with a knockout of GPx1 accelerating atherosclerosis progression." (PMID 32084149, 2020). "Ebselen, a lipid-soluble seleno-organic compound that mimics the activity of GPx1, has reported being effective in counteracting atherosclerosis of diabetic ApoE KO mice." (PMID 32630452, 2020). "The importance of Gpx1 activity is very apparent in apoE-/-/Gpx1-/-mice which display greatly accelerated atherosclerosis development, which is attenuated by treatment with the GPx mimetic, ebselen." (PMID 32084149, 2020). "In cases of coronary artery disease and atherosclerosis, GPX-1 activity is considered as a marker for both disease and levels of ROS." (PMID 31510091, 2019). "The double knockout [(ApoE−/−)/(GPx-1−/−)] mice developed more aggressive atherosclerosis compared to their (ApoE−/−) controls." (PMID 30140678, 2018). "In fact, GPX1 shortage determines increasing foam cell formation by oxLDL-C, enhancing atherosclerosis process." (PMID 30050655, 2018). "The S-sulfhydrated proteins appeared as bands on western blotting from low-molecular-weight proteins to high-molecular-weight proteins, including the band corresponding to GPx1, which is involved in cellular response to stress during atherosclerosis." (PMID 29518145, 2018). "Our results have shown that the modified Eb analogue, ME, attenuates oxidative stress, atherosclerosis and the hallmarks of diabetic nephropathy in the diabetic ApoE/GPx1 dKO mouse." (PMID 23874911, 2013). "The present study extends our previous results on atherosclerosis development in GPx-1−/−ApoE−/− mice on the cellular level." (PMID 23991041, 2013).